DYRK1B (dual specificity tyrosine phosphorylation regulated kinase 1B)
Diseases named in the same sentence as DYRK1B in open-access papers (continued):
Sharing a sentence is not in itself a finding about the gene and the disease.
pancreatic cancer (14 papers, 2010 to 2025). "Dyrk1B is implicated and highly expressed in pancreatic cancer." (PMID 38675189, 2024). "Taken together, literature has accrued numerous evidences for cell-intrinsic roles of DYRK1B in (pancreatic) cancer, affecting signal transduction, proliferation, metabolism, and cell survival." (PMID 39863750, 2025). "Even though DYRK1B is a promotor of quiescence, expression of DYRK1B is paradoxically elevated in around 40% of pancreatic tumors." (PMID 39863750, 2025). "In similar studies inhibiting DYRK1A with Harmine improved the efficacy of Imatinib in clearing gastrointestinal cancer in mice, while DYRK1B inhibition combined with Gemcitabine was shown to improve pancreatic cancer cell killing in vitro." (PMID 37608096, 2023). "Nevertheless, depletion of DYRK1B decreased colony formation of pancreatic cancer and lung cancer cells." (PMID 34830933, 2021). "In order to analyze the issue of kinetics further, we knocked down endogenous DYRK1B in human Panc1 pancreatic cancer cells by two different approaches: 1)." (PMID 27903983, 2017). "In the present study we show that interfering with DYRK1B dramatically impairs SMO-independent GLI1 expression in RAS mutant pancreatic cancer cells and phenocopies the anti-tumorigenic effect of GLI1 targeting." (PMID 26784250, 2016). "Intriguingly, up to 10 percent of pancreatic cancers harbor genomic amplifications of DYRK1B and display DYRK1B overexpression in the epithelial compartment of the tumors." (PMID 26784250, 2016). "DYRK1B is over-expressed due to gene amplification in certain tumours, including pancreatic cancer, and this has led to the suggestion that DYRK1B is a potential oncogene." (PMID 26346493, 2016). "Mutant K-ras has been shown to activate the serine/threonine kinase Mirk/dyrk1B through the Rac1/MKK3 signaling pathway so Mirk should be an active kinase during pancreatic cancer development." (PMID 25352950, 2014). "The kinase Mirk/dyrk1B is activated by oncogenic K-ras in pancreatic cancer cells and mediates their survival, at least in part, through lowering ROS levels by increasing transcription of at least three antioxidant genes." (PMID 24281169, 2010). "Additionally, DYRK1B depletion or inhibition in ovarian, lung, and pancreatic cancer cells rendered cells sensitive to chemotherapeutics that induce reactive oxygen species (ROS), such as cisplatin." (PMID 39863750, 2025). "Roughly 10% of pancreatic cancer harbor an amplification of the DYRK1B gene." (PMID 39863750, 2025). "Similarly, SOD2 was significantly upregulated by the kinase Mirk/Dyrk1B in quiescent pancreatic cancer cells." (PMID 40520023, 2025). "The human Dyrk1A gene is located on chromosome 21 in the Down syndrome critical region and is associated with Down syndrome and neurodegenerative diseases, whereas the human Dyrk1B gene is located on chromosome 19q13.2, a region often amplified in ovarian and pancreatic cancer." (PMID 38675189, 2024). "In addition, Dyrk1B inhibition by RO5454948 sensitized the pancreatic cancer cell lines Panc1 and SU86.86 to gemcitabine, as well as the colorectal cancer cell line SW620 to cisplatin." (PMID 38675189, 2024). "However, recent studies showed that DYRK1B expression was elevated in quiescent pancreatic cancer cells, and overexpression of DYRK1B induced the G1/S phase arrest via phosphorylation at Thr286 and proteasome-dependent turnover of Cyclin D131,32." (PMID 33500384, 2021). "Phosphorylation by DYRK1B results in the degradation of cyclin D1 and stabilization of p27, leading to G0 arrest, thereby reducing chemosensitivity in many cancers especially in pancreatic cancer." (PMID 34490236, 2021). "Indeed, knockdown of CIRBP sensitized pancreatic tumors to gemcitabine treatment by diminishing DYRK1B expression and increasing the ratio of ERK/p38 activity." (PMID 34490236, 2021).
pancreatic cancer (continued). "Recently, our own group has provided evidence for a critical positive role of DYRK1B rather than DYRK1A in various human cancer entities and shown that genetic and pharmacologic DYRK1B targeting can efficiently eliminate GLI1-dependent tumor-initiating pancreatic cancer cells." (PMID 28122581, 2017). "In addition, we analyzed the role of DYRK1B in the regulation of GLI1 expression in pancreatic cancer and Ewing sarcoma cells, where TGFβ/RAS and the EWS-FLI1 oncogene, respectively, control GLI1 expression independent of canonical SMO activity." (PMID 26784250, 2016). "In agreement with the previous data in SUFU-deficient and pancreatic cancer cells, inhibition of DYRK1B but not of DYRK1A reduced GLI1 protein levels." (PMID 26784250, 2016). "To test whether DYRK1B contributes to the control of GLI1 expression in pancreatic cancer cells, we analyzed PANC-1 cells for GLI1 expression in response to DYRK1 inhibition." (PMID 26784250, 2016). "Targeting DYRK1B may therefore overcome the inefficient therapeutic response of pancreatic cancer patients to SMO-inhibitors that target canonical paracrine signaling in the tumor environment rather than non-canonical GLI activity in the epithelial tumor compartment." (PMID 26784250, 2016). "We have shown that genetic and chemical perturbation of DYRK1B represses the expression of the GLI1 oncogene in a variety of settings, including human brain and pancreatic cancer and murine basal cell carcinoma cells." (PMID 26784250, 2016). "Taken together, these results demonstrate that inhibition of DYRK1B efficiently represses GLI1 expression and reduces the malignant properties of GLI1 dependent cancer cells including pancreatic cancer cells with resistance to SMO inhibitors." (PMID 26784250, 2016). "Importantly, DYRK1B targeting abolished GLI1 expression in SMO-inhibitor sensitive and SMO-inhibitor resistant cells including SUFU deficient medulloblastoma, GLI1-dependent pancreatic cancer and Ewing sarcoma cells expressing GLI1 in response to the EWS-FLI1 oncoprotein." (PMID 26784250, 2016). "In line with in vitro data, stable knockdown of DYRK1B effectively abolished the engraftment and in vivo tumor growth of PANC-1 and L3.6pl pancreatic cancer cells." (PMID 26784250, 2016). "In fact, in pancreatic cancer cells, mutant KRAS activates DYRK1B via RAC1, a member of the RHO family and the combinatory depletion of DYRK1B and KRAS led to strongly reduced cancer cell viability, which is of high interest in light of recently developed small molecule KRAS inhibitors." (PMID 39863750, 2025). "Having shown that GLI1 expression in PANC-1 cells depends on DYRK1B, we therefore addressed whether inhibition of DYRK1B is able to phenocopy the anti-tumorigenic effect of GLI1 inhibition in pancreatic cancer cells." (PMID 26784250, 2016). "In agreement with the critical role of DYRK1B in GLI1 expression, RNA-interference against DYRK1B but not against DYRK1A inhibited clonogenic growth of GLI1-dependent pancreatic cancer cells." (PMID 26784250, 2016).
Hypertension (7 papers, 2019 to 2025). The presence of chronic increased pressure in the systemic arterial system. "Studies have revealed associations between DYRK1B mutations and metabolic disorders such as coronary artery disease, hypertension, and diabetes." (PMID 40799825, 2025). "Mutations in DYRK1B were associated with a clinical phenotype that is characterized by central obesity, hypertension, type II diabetes and early-onset coronary artery disease." (PMID 31805863, 2019). "We detected a novel missense variant of the dual-specificity tyrosine phosphorylation regulated kinase lB gene (DYRK1B), c.1522C>T p.P508S, in a 4-year-old Bangladeshi obese male with BMI of 35 kg/m2 with type 2 diabetes, hypertension, fatty liver with hepatomegaly, and signs of insulin resistance." (PMID 37329217, 2023).
Obesity (7 papers, 2021 to 2025). Accumulation of substantial excess body fat. "For example, rare variants in the DYRK1B gene were found to be responsible for monogenic obesity with type-2 diabetes." (PMID 40024983, 2025). "Interestingly, it was recently reported in patients that hereditary DYRK1B mutations with a complete loss-of-function of DYRK1B (in all tissues) was associated with a substantially increased risk of obesity (odds ratio of 8) and type 2 diabetes." (PMID 40002350, 2025). "Furthermore, the pathogenic R349W mutation in DYRK1B, associated with monogenic obesity and type 2 diabetes, also disrupted autophosphorylation." (PMID 41444824, 2025). "The results of our study shed light on the potential therapeutic effects of KS-40070, a novel selective DYRK1B inhibitor, in the context of metabolic disorders such as obesity, diabetes, and fatty liver disease." (PMID 40799825, 2025). "Overall, research into the role of DYRK1B in metabolic diseases is ongoing and continues to uncover its significance in the pathophysiology of obesity, diabetes, and related metabolic disorders." (PMID 40799825, 2025). "Our study demonstrates that KS-40070, a selective DYRK1B inhibitor, has significant therapeutic potential for treating metabolic disorders such as obesity, type 2 diabetes, and fatty liver disease." (PMID 40799825, 2025). "Moreover, obesity is strongly linked to the presence of sleep-disordered breathing (SDB), suggesting an interconnected relationship between DYRK1B activity, cardiac dysfunction, obesity, and sleep-disordered breathing." (PMID 40002350, 2025). "Additionally, subsequent gene silencing analysis revealed that knockdown of DYRK1B resulted in decreased expression of Perilipin, a key protein involved in lipid droplet formation, suggesting a role for DYRK1B in lipid formation and its potential impact on obesity." (PMID 40799825, 2025).
type 2 diabetes (7 papers, 2019 to 2025). "In this study, after analyzing the sequence of all DYRK1B exons in a sample of 968 adult, including 509 with type 2 diabetes (SIGMA-ExAC), we found 29 variants." (PMID 34193236, 2021). "Here, we describe two novel DYRK1B mutations as causative of AOMS3 in two families previously misdiagnosed with type 2 diabetes." (PMID 34193236, 2021). "All DYRK1B exons were analyzed in a sample of 509 unrelated adults with type 2 diabetes and 459 controls, all belonging to the DMS1 SIGMA-cohort (ExAC)." (PMID 34193236, 2021). "Dysregulation of DYRK1B activity in the liver has been shown to affect glucose metabolism, leading to increased gluconeogenesis and elevated blood glucose levels, characteristic features of type 2 diabetes mellitus." (PMID 40799825, 2025).
diabetes (6 papers, 2021 to 2025). "Collectively, these findings provide new insights into the role of DYRK1B in glucose metabolism and identify it as a new therapeutic target for treating diabetes." (PMID 40287828, 2025). "Importantly, we observed elevated expression of DYRK1B in diabetic mice, suggesting it as a potential therapeutic target for diabetes." (PMID 40287828, 2025). "Both blood glucose levels and weight gain were significantly improved by AZ191 injection, suggesting that DYRK1B could be a potential drug target for the treatment of diabetes." (PMID 40287828, 2025). "Moreover, it implies that combining inhibitors for both DYRK1A and DYRK1B could potentially offer a comprehensive approach to diabetes treatment, opening new avenues for targeted diabetes therapies that consider both β-cell proliferation and HGP." (PMID 40287828, 2025). "The CELF2-related AS events of NECTIN2, DYRK1B, SF1 and FN1 were significantly different and may be potential therapeutic targets for diabetes-related vascular disease." (PMID 40692719, 2025).
Insulin resistance (5 papers, 2021 to 2025). Increased resistance towards insulin, that is, diminished effectiveness of insulin in reducing blood glucose levels. "Dyrk1b causes insulin resistance by increasing plasma membrane sn-1,2-diacylglycerol, leading to translocation of PKCε and reduced IRK activity." (PMID 34855620, 2022). "We next investigated whether Dyrk1b causes hepatic insulin resistance (IR), commonly associated with NAFLD and T2D." (PMID 34855620, 2022). "In addition, DYRK1B increases glucose-6-phosphatase, which is strongly associated with insulin resistance, explaining the metabolic phenotypes characterizing AOMS3." (PMID 34193236, 2021). "Eventually, the increased DYRK1B levels led to hepatic insulin resistance, which could be restored by depletion of DYRK1B." (PMID 39863750, 2025). "Moreover, a recent study showed DYRK1B to be upregulated in patients with nonalcoholic fatty liver disease and insulin resistance." (PMID 39863750, 2025). "We assessed whether KS-40070 suppression of DYRK1B restore glucose tolerance and insulin resistance in DIO mice after oral treatment with 50 or 100 mg/kg, twice daily for 9 days." (PMID 40799825, 2025).
lung carcinoma (5 papers, 2012 to 2024). "Lung cancer is a relevant model for the study of DYRK1B overexpression because DYRK1B acts as a survival factor in lung cancer cells." (PMID 39482615, 2024). "DYRK1B is overexpressed in cancer cell lines and tumor samples from various types of solid tumors including lung cancer." (PMID 39482615, 2024). "Conversely, DYRK1A and DYRK1B increases chemoresistance in gastric, ovarian, breast, and lung cancers." (PMID 33804169, 2021). "Our recent studies have found Mirk/Dyrk1B is overexpressed in a wide spectrum of cell lines and tumor specimens of ovarian and lung cancers." (PMID 23311607, 2013). "Our recent study also found Mirk/Dyrk1B was overexpressed in a wide spectrum of cell lines and tumor specimens of lung cancer." (PMID 22159921, 2012). "Moreover, elevated expression of DYRK1B was found in nearly 90% of lung cancer tumor specimens." (PMID 39482615, 2024).
colon carcinoma (4 papers, 2013 to 2024). "In one early study, colon carcinoma cells transfected with Dyrk1B exhibited increases in cell number compared with controls under serum starvation condition." (PMID 26307683, 2015). "Among them, the 3-(4-hydroxyphenyl), 5-(3,4-dihydroxyphenyl)-1H-pyrazolo [3,4-b] pyridine inhibitor (compound 8h), which exhibits the highest inhibition for Dyrk1B with IC50 of 3 nM, showed remarkable cytotoxicity in the colon cancer cell lines RKO, HCT116, DLD-1, SW480, and SW620." (PMID 38675189, 2024).
fatty liver (4 papers, 2022 to 2025). "Elevated hepatic Dyrk1b levels cause hyperlipidemia and hepatic steatosis in a kinase-independent fashion." (PMID 34855620, 2022). "We reasoned that the major traits of the mutation carriers, hypertriglyceridemia, fatty liver disease, and T2D, are the consequence of altered hepatic glucose and lipid metabolism, and embarked on characterizing the hepatic function of Dyrk1b." (PMID 34855620, 2022). "Further mechanistic studies revealed that Dyrk1b spontaneously causes fatty liver in rodents by increasing de novo lipogenesis and hepatic fatty acid uptake, despite suppressing the canonical insulin signaling by PKC epsilon-mediated insulin receptor inactivation." (PMID 37242206, 2023). "One such factor that was recently discovered is Dyrk1b, which is increased transcriptionally in fatty liver disease." (PMID 37242206, 2023). "In conclusion, Dyrk1b knockdown confers significant protection against diet-induced hepatic steatosis and hypertriglyceridemia." (PMID 34855620, 2022). "In conclusion, our findings demonstrate that Dyrk1b is highly expressed in NASH, activates mTORC2, and causes hypertriglyceridemia, fatty liver, and hepatic IR." (PMID 34855620, 2022). "At the molecular level, we have discovered metabolic pathways by which Dyrk1b induces hepatic steatosis (a) by activating mTORC2 and augmenting DNL and (b) by upregulating Fabp1 and CD36 and increasing FA influx into the liver." (PMID 34855620, 2022). "Conversely, knockdown of Dyrk1b was protective against high-calorie-induced hepatic steatosis and fibrosis and hyperlipidemia." (PMID 34855620, 2022). "Altogether, Dyrk1b levels are increased in diet-induced fatty liver disease in mice and in humans with NASH." (PMID 34855620, 2022). "Secondly, increased expression of Dyrk1b is sufficient for the development of hyperlipidemia, fatty liver disease, liver inflammation, and fibrosis on CD." (PMID 34855620, 2022). "Next, we examined the effect of global Dyrk1b disruption on the development of fatty liver." (PMID 34855620, 2022). "Reduced Dyrk1b protects against diet-induced hepatic steatosis and hypertriglyceridemia." (PMID 34855620, 2022). "We next embarked on a genetic rescue study to establish the role of mTORC2 as a mediator of Dyrk1b-induced DNL, hepatic steatosis, and hypertriglyceridemia." (PMID 34855620, 2022). "Altogether, these results indicate that mTORC2 mediates the effects of Dyrk1b in induction of DNL, hepatic steatosis, fibrosis, and inflammation." (PMID 34855620, 2022). "Altogether, these data indicate that hepatic, but not global, reduction of Dyrk1b confers significant protection against diet-induced hepatic steatosis." (PMID 34855620, 2022). "However, Dyrk1b–/– mice on HCD were not protected against hyperlipidemia or hepatic steatosis, in contrast to Dyrk1bAAV-shRNA mice." (PMID 34855620, 2022).
heart failure (4 papers, 2023 to 2025). Inability of the heart to pump blood at an adequate rate to meet tissue metabolic requirements. "In addition, acquired mutations in DYRK1B, which is overexpressed in many types of tumors and has a functional mutation associated with CV disease, support the genetic connection between heart failure and cancer." (PMID 38404658, 2024). "As frequently observed in patients with heart failure, the mean levels of C-reactive protein were significantly higher in patients with elevated DYRK1B expression levels." (PMID 40002350, 2025). "Considering the DYRK1B-signaling pathway as a new potential point of intervention, further research is needed to gain better understanding of the underlying mechanisms and whether it conveys additional therapeutic benefits compared to current heart failure medications." (PMID 40002350, 2025). "Based on these findings, DYRK1B represents a promising molecular target in patients with heart failure and reduced ejection fraction as well in patients with sleep-disordered breathing." (PMID 40002350, 2025). "The recent research has found that DYRK1B plays an important role in mitochondrial bioenergetics and the progression of cardiac hypertrophy and heart failure." (PMID 36816019, 2023). "Besides the echocardiographic data, we found several other heart failure parameters pathologically altered in patients with elevated myocardial DYRK1B levels." (PMID 40002350, 2025). "Notably, heart failure is mainly characterized by left ventricular dysfunction, and we analyzed the DYRK1B expression in atrial biopsies due to the limited availability of ventricular samples." (PMID 40002350, 2025). "Thus, DYRK1B appears to be a promising molecular target for developing new therapeutic strategies against heart failure and potentially SDB, which will be tested in future studies." (PMID 40002350, 2025). "DYRK1B represents a promising molecular target to tackle heart failure from another angle." (PMID 40002350, 2025). "We also found a trend toward higher NYHA classes in patients with an increased DYRK1B expression (p = 0.08 for NYHA class IV), suggesting higher heart failure symptoms." (PMID 40002350, 2025). "Notably, the authors found a remarkable upregulation of myocardial DYRK1B expression in mice with afterload-induced heart failure in a model of transverse aortic constriction (TAC), whereby the DYRK1B knockout mice remained protected from HF development." (PMID 40002350, 2025).